IL10 (interleukin 10)
Diseases named in the same sentence as IL10 in open-access papers (continued):
Sharing a sentence is not in itself a finding about the gene and the disease.
infection (continued). "In DF, elevated IL-8 and IL-10 levels were shown to be associated with severe infection, a clinical state which has so far not been seen in ZF." (PMID 26702627, 2016). "Therefore, the expression of IL-10 and IL-12 was evaluated at earlier stages of infection in the RTS11 cell line derived from Oncorhynchus mykiss macrophages." (PMID 27723816, 2016). "In order to determine whether early TNF-α/IL-10 level is associated with the risk of a patient later developing infection to specific pathogens, we sorted the patients according to their TNF-α/IL-10 ratio z-scores." (PMID 27761434, 2016). "IFN-g, IL-4, and IL-10 production in adult descendants ofschistosomotic mothers after postnatal infection - Splenocytes from animalsof the groups studied were cultured in the presence of OA or Con-A and the supernatantswere collected to measure the secreted cytokines." (PMID 26872339, 2016). "As compared to CD4-Cre-IL-10flox/flox (Cre-) control mice, Cre+ mice mounted elevated CD4+/IFNγ+ responses in the salivary glands to multiple MCMV antigens throughout the course of infection, most notably M25- and m142-specific cells at d14 pi when peak IL-10+ responses were observed in Cre- mice." (PMID 27926930, 2016). "In future, the determination of IL-6 and IL-10 serum levels may be offered by routine laboratory as one more marker to evaluate the severity of infection disease at the diagnosis." (PMID 27905908, 2016). "However, the stability and memory potential of IL-10–producing Th1 cells after primary infection, as well as their relative influence on the course of secondary infections, have, until now, been significantly understudied." (PMID 27630165, 2016). "IL-1β and IL-10 were also upregulated in goldfish (Carassius auratus) kidney-derived monocyte/macrophage cultures in vitro and goldfish kidney tissue in vivo following infection with M. marinum." (PMID 27415626, 2016). "Our results demonstrated that normal levels of IL-10 expression in treated groups were associated to low parasite burden, while high levels of IL-10 expression were associated to elevated parasite burden in mock-treated infected mice showing the role of IL-10 in maintaining the infection." (PMID 27579922, 2016). "It is interesting to note how the levels of IL-10 (a typically anti-inflammatory molecule) are strongly affected by the different effector T cell chemokine thresholds for recruitment at the site of infection as compared to TNF, which is more of a pro-inflammatory molecule." (PMID 28989808, 2016). "Clusters of pathogens appeared to group according to the hypersusceptibility status rather than the TNF-α/IL-10-fold change levels, suggesting that it is likely a risk factor for repeated infections in general, rather than to specific pathogens." (PMID 27761434, 2016). "We consequently questioned whether ICOS plays a role in the subsequent stabilization or maintenance of IL-10 expression by CD4+ T cells during infection potentially downstream of the IL-27R-dependent induction of IL-10 expression." (PMID 26459508, 2016). "Notably, the host-protective roles of IL-10 have also been demonstrated in many other infections and autoimmune conditions, establishing IL-10 as an instrumental component of the immune regulatory network operational during inflammation." (PMID 26459508, 2016). "In addition, we have studied variation of cytokine interleukin 10 (IL10) release in response to infection by Listeria monocytogenes, S. typhimurium and Staphylococcus aureus." (PMID 27128945, 2016). "The majority of IL-10−/− animals succumbed between days 7 and 11 post-infection." (PMID 27557867, 2016). "IL10 and TGFβ are thought to contribute to the establishment of infection and parasite replication." (PMID 26969511, 2016). "Thus, other mechanisms besides direct infection induce the IFN-I that drives IL-10 and iregDC development." (PMID 26808628, 2016).
infection (continued). "Since dendritic cells at the site of infection are key mediators of the antibody response, we examined the migration and activation state of dendritic cells into the lymph nodes draining the bladder (iliac) and kidneys (renal) in wild type and IL-10−/− mice." (PMID 26907352, 2016). "We have addressed the impact of elevated IL-10 production during secondary infection in shaping anamnestic immune responses and demonstrate that IL-10 may play an important role in regulating reactivation of memory CD4+ T cells." (PMID 27630165, 2016). "At this time the notion that the mast cell IL-10 response is attributable to the breakdown of the epithelial barrier following infection remains speculative." (PMID 26907352, 2016). "Notably, CD4+YFP+ T cells were the major source of IL-10 during secondary infection in all examined organs, implying that memory CD4+ T cells rapidly expanded and expressed IL-10 during secondary infection." (PMID 27630165, 2016). "Although not statistically significant (P > 0.050), mice consuming the RS diet tended to exhibit elevated expression (P ≤ 0.083) of Treg cytokines (i.e. Il-10, Tgfβ), and this was evident during peak infection as compared to mice consuming the WB and CN diets, respectively." (PMID 28031748, 2016). "One child born to CFA–ve mothers acquired infection and having IL-10 level of 9 pg/ml." (PMID 27861499, 2016). "Apart from miRNAs, several compounds such as ammonium trichloro (dioxoethylene-O, O’) tellurate (AS101), SD169 and an antihelminth niclosamide can be used to inhibit IL-10 mediated anti-inflammatory activity that has already shown promising results in various infections." (PMID 27905994, 2016). "Thus, reactivating malaria infection–induced Ag-experienced memory CD4+ T cells appear specifically programmed to rapidly become differentiated IL-10–producing cells following challenge infection." (PMID 27630165, 2016). "Taken together, these findings suggest that the antiparasitic activity (of melittin) may also be ascribed to the upregulation of IL-12 levels and the downregulation of IL-10 levels, resulting in a reduced in vitro infection." (PMID 26752985, 2016). "Proliferation might similarly contribute to IL-10 production by NK cells during Lm or other infections, though this remains to be determined." (PMID 27295349, 2016). "Interestingly, inhibition of IL-10 expression appeared to be more pronounced, particularly in the spleen and lung, when treatment was commenced on day 3 of infection than when it was commenced treatment from day −1." (PMID 26459508, 2016). "While MCMV does not encode a vIL-10, cellular IL-10 is induced upon infection of macrophages in vitro." (PMID 27926930, 2016). "IL-10 may play a role in bacterial clearance in later dates post-infection, which represents a limitation of the current studies." (PMID 27737696, 2016). "In WT, a dramatic increase in IL-10 producing cells is observed at three weeks post-infection." (PMID 27936058, 2016). "Although IL-10 can constrain Tfh differentiation following immunization, whether IL-10 plays a role in promoting or inhibiting Tfh cell differentiation, maintenance or function during infection remains less clear." (PMID 27732671, 2016). "However, as importantly, we found that ICOS also plays a role in controlling IL-10 production by CD4+ YFP+ T cells during infection." (PMID 26459508, 2016). "These in vitro studies suggest that IL-10 may play an important role in regulating the immune response to infection in young hosts, which is currently being evaluated in vivo in our laboratory." (PMID 27737696, 2016). "Then, one can also conclude that early monitoring of levels of interleukins, in particular IL-10, may contribute tomaking clinical decisions regarding the prophylaxis forfungal infections subsequent or concomitant tothe treatment of malignant tumors." (PMID 26905729, 2016).
infection (continued). "Interestingly, while JMJD3 was found to negatively regulate few of the mycobacteria-responsive M1 markers of macrophages viz., Il12, Il1b and Cxcl2, the expression of M2 markers like Arg1, Mrc1, Il10, Tgfb, Ccl17 and Ccl2 on infection were JMJD3-dependent." (PMID 27532872, 2016). "Interestingly, the production of the anti-inflammatory cytokine IL-10 was significantly decreased in Dectin-2−/− mice at day 28 after infection." (PMID 27046240, 2016). "Our results indicate that IL-10 production has little effect on DENV-ADE infection of K562 cells." (PMID 26923481, 2016). "Moreover, CD4+YFP+GFP− T cell–derived memory cells rapidly upregulated IL-10–GFP expression in the spleen during challenge infection, leading to a significant increase in generation of new CD4+YFP+GFP+ T cells in the spleen during secondary infection." (PMID 27630165, 2016). "This suggests a possible effect of IL-10 in curbing the CNS inflammatory environment to allow non-pathogenic S. epidermidis to cause infection." (PMID 27737696, 2016). "This infection decreased the migratory capacity of the hDFSCs by 50%, did not disturb hDFSC differentiation potential and provoked an increase in IL-6 and IL-8 secretion while leaving IL-10 levels unaltered." (PMID 27974831, 2016). "In contrast, anti-inflammatory responses involving IL-10 and other mediators could potentially weaken resistance to infection, while contributing to healthy aging." (PMID 27322555, 2016). "Thus, after infection of hDFSCs or Ca9-22 with P. intermedia or T. forsythia accumulation of interleukins IL-6, IL-8 and IL-10 in the supernatant was quantified after 2 h, 4 h and 24 h of anaerobic co-culture (MOI = 100)." (PMID 27974831, 2016). "IL-10 has emerged as a key immunoregulator during infection." (PMID 26903968, 2016). "Interestingly, this increase in inflammatory response to microbes does not necessarily result in increased clearance of the organism, suggesting that the role of IL-10 in response to infection is likely pathogen-specific." (PMID 27737696, 2016). "Moreover, we show that the combined activity of interferon-gamma and interleukin-10 limits the magnitude of infection-induced Tfh responses, the secretion of parasite-specific secreted antibody, and parasite control." (PMID 27732671, 2016). "Furthermore, forelimb grip strength and nociceptive pain sensitivity, measures of motor and pain-sensing neural activity, in infected IL-10−/− mice became significantly different from WT mice on days 8 and 14 post-infection, respectively." (PMID 27557867, 2016). "In the second line, the cAMP-mediated downregulation of pro-inflammatory IL-12 and TNF-α production and the upregulation of anti-inflammatory IL-10 cytokine release by myeloid cells, would skew the adaptive immune responses to infection and protract bacterial colonization." (PMID 27581058, 2016). "IL-10 is a potent immunoregulatory cytokine that might be beneficial in the course of infection by attenuating the excessive host inflammatory response induced by upregulated pro-inflammatory cytokines and thus controlling immunopathology." (PMID 27301272, 2016). "During acute infection with L. interrogans serovar Icterohaemorrhagiae, hamsters upregulate gene expression of TNF-α, TGF-β, IP-10 (CXCL10), and IL-10 at the site of infection (kidney) and peripheral blood mononuclear cells upregulate expression of TNF-α, IFN-γ, IL-12." (PMID 27486445, 2016). "What additional factor(s) might contribute to driving NK cell transitioning from IFNγ to IL-10 production during Listeria and other infections remains to be determined." (PMID 27295349, 2016). "In addition, infection of MFs by Leishmania also leads to the production of immunoregulatory cytokines, such as IL-10 and TGF-β, which are known for their ability to inhibit or deactivate MF functions (see Evasion of Innate Immunity)." (PMID 27303406, 2016). "Larger production of IL-10 was found in gp91phox−/− mice 16 weeks after infection." (PMID 27056545, 2016).
infection (continued). "The fate of these CD4+IFN-γ+IL-10+ T cells following clearance of primary infection and their subsequent influence on the course of repeated infections is, however, presently unknown." (PMID 27630165, 2016). "Moreover, while the extent of upregulation of IL6 by infection remained similar in both breeds (~6.8 fold), overexpression of both IL10 and IL13 mRNA molecules was more profound in the resistant breed (CHB) than in CS." (PMID 27197554, 2016). "Additionally, IL-10 production by NK cells was shown to impair immunity during infection with the parasite Leishmania." (PMID 27295349, 2016). "Interestingly the reduction in the serum levels of IL-10 reached statistically significance only in L. amazonensis co-infected group at days 5 and 10 post P. yoelii 17XNL infection." (PMID 27446022, 2016). "However, the production of IL-6, TNFα and IL-10 in response to infection with F. tularensis LVS, S. aureus or P. aeruginosa was similar between WT (C57BL/6N) and Nlrp12−/− BMDM." (PMID 27779193, 2016). "Tbet deficient mice did however display a reduction in lung Il10 mRNA levels after infection, suggesting a possible deficiency in IL-10 production from a non-helper T cell source." (PMID 27683080, 2016). "IL-10 is produced by different cell type in both acute and chronic phase of infection." (PMID 26982706, 2016). "chagasi-infection, with emphasis on the immunopathogenic role of IL-6 and IL-10 which may aid in preventing or reducing the morbidity of severe AVL." (PMID 27051668, 2016). "However, the numbers of Ly6C− macrophages in brains of infected IL-10−/− animals were greater compared to infection-matched WT animals and uninfected controls." (PMID 27557867, 2016). "Notably, CD4+ T cells constituted a significantly higher fraction of the IL-10+ cells in the liver during the early stages of secondary compared with primary infection." (PMID 27630165, 2016). "In murine studies, IL-10 expression also occurs in response to murine infection with C. albicans, H. capsulatum and A. fumigatus and the absence of IL-10 is associated with improved fungal clearance." (PMID 27973396, 2016). "Interactions with macrophage surface molecules, including the complement receptor, also plays a role in the activation of protein kinase regulated by RNA (PKR), which induces the release of IFNα, IL-27, and IL-10 among other cytokines that also modulate the host response to infection." (PMID 27148265, 2016). "To test this hypothesis, we implanted S. epidermidis-infected catheters into the CNS of wild-type C57BL/6 and IL-10 KO mice and compared their clinical response to infection, bacterial burdens, and inflammatory responses via multianalyte microbead array." (PMID 27737696, 2016). "However, there was a trend towards decreased expression of IL-10 mRNA after 24 h infection by X31-infected MDM." (PMID 27701435, 2016). "Similarly to ex vivo data, a significant production of IL-10 by CD4+ cells was also observed in vivo during S. suis primary infection." (PMID 27905502, 2016). "They include IL-10 found already to be upregulated by YopM at 1.5 h post infection." (PMID 27300509, 2016). "Conversely, helminth-induced IL-10-mediated immunosuppression has raised concerns for populations in which STH infections coexist with other morbidities such as HIV/AIDS, malaria, and tuberculosis, as clearance for the latter depends on an active and timely type-1 response." (PMID 27882241, 2016). "CD4+ T cell-derived IL-10 is produced by IL-4+ Th2 cells in the early phase of infection." (PMID 26195548, 2015). "Furthermore, increased numbers of CD4+ T cells were apparent in the site of infection of 4x IL-10-/- compared to 4x WT mice (Fig 1Jiversus1Jiv)." (PMID 25974019, 2015).
infection (continued). "Timely and appropriate production of these cytokines in the early phase of infection and their down regulation by anti-inflammatory cytokines such as IL-10 in the later phase of infection has been shown to be crucial for parasitaemia control and avertion of host tissue damage and severe malaria." (PMID 27350800, 2015). "The Treg cells in our experiments appeared less prone to produce IL-10 as the infection progressed." (PMID 25942314, 2015). "In addition, analysis of culture supernatant showed that infection significantly upregulated IL-10 compared with mock-spinoculated controls, whereas the presence of X4 or R5 virus did not significantly increase IL-35 production." (PMID 26482032, 2015). "Furthermore, systemic IL-10 levels have been correlated with the viral load in blood at 21 days post-infection." (PMID 28405423, 2015). "Importantly, the role of IL-10 as an anti-inflammatory agent has been more recently confirmed in cattle, primate and human infections with African trypanosomes." (PMID 26222157, 2015). "Although immunotherapeutic strategies involving the administration of exogenous interferon-gamma is found to be effective in suppressing leishmaniasis, the high production of IL10 during early stage of infection often suppresses its activity, thereby hindering NO production and disease clearance." (PMID 26660865, 2015). "Thus, although Th17 cells appear to be a common denominator in helminth-infected individuals displaying severe pathology, each type of infection appears to have created its own subtle collaboration of immune parameters such as Treg or IL-10." (PMID 25569210, 2015). "Splenocytes removed from infected animals and stimulated in vitro with a total parasite extract (FhTE) produced high levels of IL-4, IL-5 and IL-10, with significant higher levels of IL-4 and IL-10 as soon as the first wpi, reaching a plateau at week 2 after infection." (PMID 26720149, 2015). "We hypothesize that the lower production of IL-10 in staphylococcal IE could explain, at least in part, the more exacerbated inflammatory response and the higher clinical impact of this infection." (PMID 26225421, 2015). "Speculatively, elevated TNF-α and reduced IL-10 in avian influenza virus infected PAM could indicate a more balanced paracrine/endocrine pro-inflammatory signature during infection." (PMID 26642934, 2015). "In this sense, the action of PLA2 impeded the parasite from maintaining its escape mechanism, a fact also observed in a prior study that measured the production of TNF-α, NO, and IL-10 in treatment with PLA2 from B. pauloensis in experimental infection of murine macrophages with L. amazonesis." (PMID 26609302, 2015). "Taken together, these data suggest that apart from the absolute amount of each cytokine, the balance between pro-inflammatory (IFN-γ and TNF-α) and anti-inflammatory (IL-10) cytokine responses to Rv2031 could determine the outcome of infection." (PMID 25897840, 2015). "The increase in expression of mRNA encoding Il10 within vaginal samples collected at 35 days after infection was not expected." (PMID 26779389, 2015). "In addition, regulatory T cells, both innate (nTregs) and adaptive (aTregs), are also known to be major producers of IL-10 in immunity to infections." (PMID 26417443, 2015). "This is an important finding, as it suggests that strains of parasite that are able to induce a more balanced response, with TNF-alpha and IL-10 production, may lead to a better infection outcome." (PMID 26147698, 2015). "In addition and as shown in S1 Fig, CD3+ T cells were the major producers of IFN-γ, TNF-α and IL-10 in the spleens throughout the infection." (PMID 25875604, 2015). "Thus, the possibility that IL-10 secreted by CD4+ T cells during infection is responsible of MHC class II decrease on DCs cannot be ruled out." (PMID 26720149, 2015).